IRAK3 (interleukin 1 receptor associated kinase 3)
Description:
Putative inactive protein kinase which regulates signaling downstream of immune receptors including IL1R and Toll-like receptors. Inhibits dissociation of IRAK1 and IRAK4 from the Toll-like receptor signaling complex by either inhibiting the phosphorylation of IRAK1 and IRAK4 or stabilizing the receptor complex (By similarity). Upon IL33-induced lung inflammation, positively regulates expression of IL6, CSF3, CXCL2 and CCL5 mRNAs in dendritic cells.
Synonyms: IRAK-M; ASRT5; IRAKM
Tractability: Small molecule: a structure with a bound ligand is known; a high-quality ligand is known; it belongs to a druggable protein family. Antibody: its Gene Ontology location is reachable by antibodies, with medium confidence. PROTAC: it is named in the literature on targeted protein degradation; ubiquitination databases record sites on it; its protein half-life has been measured; a small molecule that binds it is known.
Target class: Kinase; TKL protein kinase IRAK family; TKL protein kinase group; Enzyme; Protein Kinase
Chemical probes: IRAK3-PROTAC 23 (high quality)
Gene: Protein-coding gene on chromosome 12 (66,188,995 to 66,254,622, forward strand). Ensembl gene ENSG00000090376.
Subcellular location: Cytoplasm; Nucleus
Subcellular location (Human Protein Atlas): Vesicles
Pathways (Reactome):
Immune System: Interleukin-1 signaling; MyD88:MAL(TIRAP) cascade initiated on plasma membrane
Gene Ontology:
Molecular function: ATP binding; magnesium ion binding; protein binding; protein heterodimerization activity; protein homodimerization activity; protein kinase binding; protein serine/threonine kinase activity; identical protein binding; protein kinase activity
Biological process: interleukin-1-mediated signaling pathway; lipopolysaccharide-mediated signaling pathway; negative regulation of canonical NF-kappaB signal transduction; negative regulation of interleukin-12 production; negative regulation of interleukin-6 production; negative regulation of MAPK cascade; negative regulation of protein catabolic process; negative regulation of protein-containing complex disassembly; negative regulation of tumor necrosis factor production; protein phosphorylation; response to interleukin-1; cytokine-mediated signaling pathway; intracellular signal transduction; MyD88-dependent toll-like receptor signaling pathway; negative regulation of cytokine-mediated signaling pathway; negative regulation of innate immune response; negative regulation of macrophage cytokine production; negative regulation of toll-like receptor signaling pathway; positive regulation of canonical NF-kappaB signal transduction; positive regulation of macrophage tolerance induction; regulation of protein-containing complex disassembly; response to exogenous dsRNA; response to lipopolysaccharide; response to peptidoglycan; response to virus; and 6 more
Cellular component: cytoplasm; nucleus; plasma membrane
Genetic constraint (gnomAD): Loss-of-function variants: 35 observed, 34.31 expected, observed/expected ratio (o/e) 1.02, 90% interval 0.78 to 1.35. The upper end of that interval is the gene's LOEUF score, 1.35, which puts it in group 5 of 6, group 1 being the genes least tolerant of losing a copy. Missense variants: 572 observed, 586.63 expected, observed/expected ratio (o/e) 0.98, 90% interval 0.91 to 1.04. Synonymous variants: 217 observed, 212.66 expected, observed/expected ratio (o/e) 1.02, 90% interval 0.91 to 1.14.
Homologues: Orthologues: chimpanzee IRAK3 (99% identical), macaque IRAK3 (97% identical), dog IRAK3 (83% identical), pig IRAK3 (81% identical), rabbit IRAK3 (78% identical), rat Irak3 (77% identical), guinea pig IRAK3 (77% identical), mouse Irak3 (76% identical), zebrafish irak3 (38% identical), Caenorhabditis elegans pik-1 (17% identical), Drosophila melanogaster pll (17% identical), Caenorhabditis elegans hasp-1 (7% identical), and 3 more. Paralogues in human: IRAK1 (28% identical), IRAK2 (21% identical), IRAK4 (19% identical), HASPIN (11% identical).
Diseases named in the same sentence as IRAK3 in open-access papers:
IRAK3 is named in the same sentence as 116 diseases in open-access papers, as found by Europe PMC text mining. Sharing a sentence is not in itself a finding about the gene and the disease. The quoted sentences say what the papers report.
Sepsis (37 papers, 2010 to 2026). Sepsis is defined as life-threatening organ dysfunction caused by a dysregulated host response to infection. "Interleukin-1 receptor associated kinase 3 (IRAK3) is a key regulator of inflammation and has been linked to endotoxin tolerance and sepsis." (PMID 40108736, 2025). "IRAK3 is associated with the immunosuppression phase of sepsis and also endotoxin tolerance that is one mechanism underlying the immunosuppression." (PMID 35167625, 2022). "Analyses of differentially expressed genes in sepsis have shown that the Interleukin-1 receptor associated kinase 3 (IRAK3) is among the genes whose expression is increased in Toll-like receptor (TLR) signalling pathways." (PMID 36423191, 2022). "A positive association between IRAK3 single nucleotide polymorphisms and sepsis susceptibility was reported in a Han Chinese population." (PMID 35167625, 2022). "The immunosuppression during sepsis is associated with an upregulation of IRAK3 mRNA and protein expression." (PMID 35167625, 2022). "IRAK3 gene expression was upregulated in blood samples from patients with sepsis, and associated with susceptibility to severe sepsis, poor outcomes and mortality." (PMID 35167625, 2022). "IRAK3 is associated with many inflammatory diseases, including sepsis, and is required in endotoxin tolerance to maintain homeostasis of inflammation." (PMID 33382782, 2020). "Tier 2 sepGIKs included 89 sepGIKs (399 pairs), such as FFAR2 (free fatty acid receptor 2), CCR7 (C-C chemokine receptor type 7), HK3 (hexokinase 3), and IRAK3 (interleukin-1 receptor-associated kinase 3), which were differentially expressed in at least 14 sepsis datasets." (PMID 40761792, 2025). "Additionally, CD177 showed significantly increased expression in sepsis patients, whereas IRAK3 is associated with the immune suppression stage." (PMID 38332910, 2023). "Moreover, increased expression of IRAK3 is associated with a decreased capacity to release proinflammatory cytokines from mononuclear cells in patients with sepsis after stimulation with LPS, and are also closely related to poor prognosis." (PMID 34757596, 2022). "Clinically, upregulation of the IRAK3 gene nearby rs1732887 was observed in monocytes from patients of sepsis, one of the major causes of acute lung injury, suggesting that rs1732887 might confer risk for acute lung injury by upregulating IRAK3 gene expression." (PMID 38459946, 2024). "Through bioinformatics approaches, this study successfully identified five genes (IRAK3, S100A9, TXN, NFATC2, and GSTO1) associated with programmed cell death in the context of sepsis." (PMID 40108736, 2025). "Our analysis showed that the expression of IRAK3 increased in the control group, mild sepsis group and severe sepsis group in a gradient pattern, which was consistent with the results of previous literature." (PMID 40108736, 2025). "Meta-analyses of in vivo studies substantiate the roles of IRAK3 during the immunosuppression phase of sepsis." (PMID 38348451, 2024). "Moreover, to ascertain whether these diagnostic genes also possessed good clustering capabilities across different sepsis groups, an intersection was made between the machine learning-selected diagnostic genes and key cluster genes, resulting in two intersecting genes (IRAK3, CD177)." (PMID 38332910, 2023). "Beyond these confirmed genes, this study also discovered three potential diagnostic genes for IE (CD177, IRAK3, RNASE2) and one potential diagnostic gene for sepsis (RNASE2) for the first time." (PMID 38332910, 2023). "Many studies using in vivo animal (mainly rodent) models investigated IRAK3 and cytokine expression under various disease conditions (e.g., sepsis, colitis, asthma, ischemia reperfusion injury)." (PMID 35167625, 2022). "Interleukin-1 receptor associated kinase 3 (IRAK3) is a critical modulator of inflammation and is associated with endotoxin tolerance and sepsis." (PMID 35167625, 2022).
Sepsis (continued). "The effect of IRAK3 in sepsis has been investigated widely using cell culture, clinical samples, and in vivo animal and human models." (PMID 35167625, 2022). "There are genes such as Interleukin-1 receptor-associated kinase 3 (IRAK3), Adrenomedullin (ADM), and arachidonate lipoxygenase 5 (ALOX5), whose expressions were significantly upregulated in sepsis patients." (PMID 36298439, 2022). "The inhibitory effect of IRAK3 following two-challenges was confirmed with meta-analyses by both in vivo and in vitro studies, and correlates to clinical outcomes, indicating the importance of IRAK3 in immunosuppression phase of sepsis." (PMID 35167625, 2022). "At ST (1h) following ex vivo challenge with LPS, IRAK3 mRNA expression in samples of patients with sepsis further increases compared to unchallenged samples and healthy subjects, and this corresponds to two-challenge animal in vivo models." (PMID 35167625, 2022). "The meta-analyses of in vivo studies further confirmed the roles of IRAK3 during immunosuppression phase of sepsis." (PMID 35167625, 2022). "This is in contrast to the results of meta-analyses of data from in vitro cell culture studies of sepsis, which revealed inhibitory effects of IRAK3 on TNF-α level at IT in cell lines and at LT in mouse primary cells after one-challenge." (PMID 35167625, 2022). "Increased expression levels of the IRAK3 gene are correlated with the development of acute lung injury in patients with severe sepsis." (PMID 33256556, 2021). "Identifying the time frames of these events in different cell models is relevant, as IRAK3 is involved in sepsis pathophysiology." (PMID 33382782, 2020). "IRAK3 mRNA expression is up-regulated in blood samples of patients with sepsis compared with healthy controls." (PMID 33382782, 2020). "Notably, miR-539-5p exhibits potential significance in the pathogenesis of LPS-induced sepsis by selectively targeting IRAK3, suggesting its potential as a therapeutic target for treating LPS-induced sepsis." (PMID 38348451, 2024). "Importantly, IRAK3 expression is elevated in blood monocytes from patients with sepsis, and even more so in septic shock." (PMID 38235139, 2023). "Our results showed hypomethylation of the IRAK3 promoter in sepsis and septic shock, which could contribute to increased circulating IRAK3 in septic and septic shock patients, thus explaining the elevated levels found in these patients." (PMID 38235139, 2023). "IRAK3 transcript expression is markedly induced in clinical samples of septic patients compared to healthy subjects, and highly correlated to severity and mortality of sepsis." (PMID 35167625, 2022). "MiR-539-5p potentially plays an important role in the pathogenesis of LPS-induced sepsis by targeting IRAK3, suggesting that miR-539-5p may be a potential new target for the treatment of LPS-induced sepsis." (PMID 34757596, 2022). "Thus, the increases of IRAK3 gene expression in patients with sepsis is more extended compared to human in vivo models where IRAK3 mRNA expression increased at ST—IT and declined to baseline at 24h." (PMID 35167625, 2022). "Hence, IRAK3 acts cooperatively with other checkpoint molecules in TLRs/IL-1R pathway to control inflammatory responses to pathogen infections during sepsis." (PMID 35167625, 2022). "The transcription factor, HIF-1α is induced in monocytes from patients with sepsis, and upregulated IRAK3 mRNA and protein expression between 0.5h to 24h as well as reducing TNF-α and IL-6 expression at IT and LT in in vitro monocytes challenged with endotoxin." (PMID 35167625, 2022). "It is necessary for more studies of IRAK3 mRNA and protein expression in human in vivo models, especially two-challenge intervention to be conducted to provide greater understanding of the role of IRAK3 in human sepsis and enhance treatment options with improved patient outcomes." (PMID 35167625, 2022).
Sepsis (continued). "The expression of IRAK3 in LPS-treated human leukocytes isincreased during early response and peaks higher and more rapidly when stimulated with LPS, which is confirmed in cells from patients with sepsis." (PMID 34757596, 2022). "This information is useful in designing experiments to explore actions of IRAK3 at the molecular level and how it influences expression of inflammatory cytokines using cell lines to model sepsis and endotoxin tolerance, with respect to different intervention chemicals and time post-treatment." (PMID 33382782, 2020). "Thus, in vitro cell culture models challenged with bacteria or LPS can mimic sepsis conditions and are useful to study the molecular functions of IRAK3 in endotoxin tolerance and sepsis." (PMID 33382782, 2020). "This review provides better understanding of the role of IRAK3 and its upstream and downstream factors in regulating inflammation following one-challenge and two-challenge interventions, and potential involvement in sepsis." (PMID 33382782, 2020). "Indeed, several recent studies have demonstrated that IRAK3 regulates critical aspects of innate immunity, including the development of endotoxin tolerance and sepsis-induced alterations of antimicrobial responses." (PMID 22272346, 2012). "IRAK-3 plays a pivotal role in innate immunity that may result in an immunocompromised state during sepsis." (PMID 21811575, 2011). "However, the mechanism of IRAK3 action on sepsis is not fully understood." (PMID 35167625, 2022). "Moreover, based on meta-analyses, the review compared the findings of IRAK3 effects and cytokine expression patterns between challenged in vitro cell culture and in vivo animal models for the study of sepsis, thereby showing the translatability of these models to human." (PMID 35167625, 2022). "Notably, IRAK3 plays a role in regulating immunosuppression in sepsis." (PMID 33382782, 2020). "IRAK-3 is a negative regulator of Toll-dependant signaling and its induction may impair innate immunity and hence result in an immunocompromised state allowing bacterial survival and systemic spread during sepsis." (PMID 21811575, 2011). "A total of 1389 DEGs such as NOV, SEPT9, XIST, ESYT1 were upregulated in sepsis, whereas 1657 DEGs such as S100A9, IRAK3, MCEMP1, TLR5, CD177 were downregulated." (PMID 41542228, 2026). "The results showed that the expression of IRAK3, S100A9, TXN and GSTO1 in the sepsis group was increased, while the expression of NFATC2 in the sepsis group was decreased (P < 0.05)." (PMID 40108736, 2025). "The expression of IRAK3 and TXN in the control group, mild sepsis group and severe sepsis group increased in a gradient manner." (PMID 40108736, 2025). "In a systematic review and meta-analysis, it was found that IRAK3 expression and its effect on inflammatory markers (TNF-α and IL-6) varied at different stages of sepsis, affected by changes in experimental procedures." (PMID 40108736, 2025). "Additional genes upregulated in sepsis include adrenomedullin (ADM), IRAK3, and arachidonate 5-lipoxygenase (ALOX5/5-LOX)." (PMID 41293242, 2025). "Expression of three biomarkers (IRAK3, RNASE2, S100A12) was visualized in both HC and sepsis samples." (PMID 38332910, 2023). "We successfully identified four key biomarkers correlated with IE and Sepsis, namely CD177, IRAK3, RNASE2, and S100A12." (PMID 38332910, 2023). "For sepsis, we noticed several inflammatory and immune-related proteins, such as IRAK1, IRAK3, IKBKB, and STAT3, in the network, suggesting overlap of the inflammatory response activated in COVID-19 and sepsis." (PMID 33156843, 2020). "However, blood samples from sepsis patients need to be tested for IRAK3, TNF-α and IL-6 protein levels at more time intervals after endotoxin challenge to clarify whether the patterns of temporal expression of these molecules reflect in vitro human cell culture models." (PMID 33382782, 2020).
Sepsis (continued). "This leads to impaired bacterial clearance and contributes to the immunosuppressive state of sepsis, while mice lacking IRAK3 exhibited improved host defense and survival." (PMID 41293242, 2025). "In order to verify the validity of the diagnostic marker genes, a KS test was performed on the GSE69063 dataset for these five genes, and the results showed that IRAK3, S100A9, TXN and GSTO1 were up-regulated in the sepsis group, while NFATC2 was down-regulated." (PMID 40108736, 2025). "Additionally, by comparing the expression profiles between disease samples and control samples, it was found that the expression levels of CD177, RNASE2, IRAK3, and S100A12 were significantly elevated in both IE and sepsis samples." (PMID 38332910, 2023). "Interestingly, Toll‐like receptor signalling was detected in sepsis, specifically in the brain (prefrontal cortex and hippocampus), via the upregulation of genes such as CD14, TLR1, TLR2, TLR3, TLR7, IRAK3 and IRAK4." (PMID 37731199, 2023). "A negative correlation between IRAK3 and TNF-α expression in rodents following two challenges demonstrates the association of IRAK3 in the immunosuppression phase of sepsis." (PMID 35167625, 2022). "IRAK3 mRNA levels in survivors of sepsis were significantly lower than in non-survivors, increased within the first five days after diagnosis, and decreased at day 28 when patients recovered." (PMID 35167625, 2022). "Further research using both human and mouse in vivo models on the actions and relations of IRAK3 to other molecules (glucocorticoids, TREM-1, HMBG1, and HIF-1α) and inflammatory regulators will clarify insights and may improve treatment of sepsis." (PMID 35167625, 2022). "However, to our knowledge, a systematic review or meta-analysis of IRAK3 effects in in vivo models for the study of sepsis has not been conducted to date." (PMID 35167625, 2022). "Additionally, sepsis non-survivors displayed higher IRAK3 mRNA expression than the survivors." (PMID 35167625, 2022).